CIAO1 (cytosolic iron-sulfur assembly component 1)
Description:
Key component of the cytosolic iron-sulfur protein assembly (CIA) complex, a multiprotein complex that mediates the incorporation of iron-sulfur cluster into extramitochondrial Fe/S proteins. As a CIA complex component, interacts specifically with CIAO2A or CIAO2B and MMS19 to assist different branches of iron-sulfur protein assembly, depending of its interactors. The complex CIAO1:CIAO2B:MMS19 binds to and facilitates the assembly of most cytosolic-nuclear Fe/S proteins. CIAO1:CIAO2A specifically matures ACO1 and stabilizes IREB2. Seems to specifically modulate the transactivation activity of WT1. As part of the mitotic spindle-associated MMXD complex it may play a role in chromosome segregation.
Synonyms: CIA1; WDR39; MMDS10
Tractability: PROTAC: ubiquitination databases record sites on it; its protein half-life has been measured.
Gene: Protein-coding gene on chromosome 2 (96,266,159 to 96,274,173, forward strand). Ensembl gene ENSG00000144021.
Subcellular location: Cytoplasm
Subcellular location (Human Protein Atlas): Nucleoplasm; Cytosol
Pathways (Reactome):
Metabolism: Cytosolic iron-sulfur cluster assembly
Gene Ontology:
Molecular function: protein binding
Biological process: iron-sulfur cluster assembly; protein maturation; regulation of transcription by RNA polymerase II
Cellular component: cytoplasm; cytosolic [4Fe-4S] assembly targeting complex; MMXD complex
Genetic constraint (gnomAD): Loss-of-function variants: 32 observed, 40.53 expected, observed/expected ratio (o/e) 0.79, 90% interval 0.6 to 1.06. The upper end of that interval is the gene's LOEUF score, 1.06, which puts it in group 4 of 6, group 1 being the genes least tolerant of losing a copy. Missense variants: 415 observed, 435.14 expected, observed/expected ratio (o/e) 0.95, 90% interval 0.88 to 1.03. Synonymous variants: 183 observed, 169.04 expected, observed/expected ratio (o/e) 1.08, 90% interval 0.96 to 1.22.
Homologues: Orthologues: macaque CIAO1 (99% identical), dog CIAO1 (97% identical), chimpanzee CIAO1 (97% identical), rabbit CIAO1 (96% identical), guinea pig CIAO1 (95% identical), mouse Ciao1 (95% identical), pig CIAO1 (95% identical), rat Ciao1 (94% identical), tropical clawed frog ciao1 (81% identical), zebrafish ciao1 (76% identical), Drosophila melanogaster Ciao1 (58% identical), Caenorhabditis elegans ciao-1 (37% identical).
Diseases named in the same sentence as CIAO1 in open-access papers:
CIAO1 is named in the same sentence as 21 diseases in open-access papers, as found by Europe PMC text mining. Sharing a sentence is not in itself a finding about the gene and the disease. The quoted sentences say what the papers report.
Alzheimer disease (1 paper, 2024). A progressive, neurodegenerative disease characterized by loss of function and death of nerve cells in several areas of the brain leading to loss of cognitive function such as memory and language. "Interestingly, heterozygosity for a variant in CIAO1 appeared to co-segregate with Alzheimer’s disease in a Japanese family." (PMID 38411040, 2024).
cholera (1 paper, 2022). "The region with the strongest signal of selection, located on chromosome 2 and encompassing five genes (NRNP200, CIAO1, ITPRIPL1, NCAPH, and TMEM127) was also the region showing the strongest association with cholera, with the top associated SNPs located between the genes NRNP200 and ITPRIPL1." (PMID 35925921, 2022).
colon cancer (1 paper, 2016). "Further analysis of RNA-seq data for CIAO1, (HEK293, 1CT, and SW620 colon cancer cells) revealed a relatively high number of reads (comparable to read numbers mapping to the flanking exons and the 3′ UTR) present in the region that corresponds to the CIAO1 penultimate intron." (PMID 26546131, 2016).
Mitochondrial myopathy (1 paper, 2024). "While the CIAO1-related muscle pathology does not fit the conventional criteria of a mitochondrial myopathy, it exhibits a discernible mitochondrial dysfunction, as demonstrated by histological, ultrastructural, and functional assessments." (PMID 38950322, 2024).
neurodegeneration with brain iron accumulation (1 paper, 2024). "Interestingly, the pattern of brain iron deposition observed in the CIAO1-deficient patients is reminiscent of that observed in patients with neurodegeneration with brain iron accumulation (NBIA), a clinically and genetically heterogenous group of disorders affecting children and adults." (PMID 38950322, 2024).
ovarian carcinoma (1 paper, 2023). A malignant neoplasm originating from the surface ovarian epithelium. "For iron utilization, a lower expression of CIAO1 and CPOX was associated with a more advanced stage of ovarian cancer." (PMID 38186569, 2023).
Respiratory insufficiency (1 paper, 2024). "Our study revealed that patients with biallelic loss of function in CIAO1 developed proximal and axial muscle weakness, fluctuating creatine kinase elevation, and respiratory insufficiency." (PMID 38950322, 2024). "Patients with loss of function in CIAO1, which is required to maintain genome integrity, experience multisystem involvement, including muscle weakness, respiratory insufficiency, and neurological comorbidities." (PMID 38950322, 2024).
cancer (3 papers, 2019 to 2026). A tumor composed of atypical neoplastic, often pleomorphic cells that invade other tissues. "CIAO1 is a novel candidate reference gene that was identified from pan-cancer transcriptome data." (PMID 37274277, 2023). "CIAO1, CNOT2, and RBM45 were the candidate reference genes used in this study and were screened as stably expressed reference genes using pan-cancer transcriptome data." (PMID 37274277, 2023).
myopathy (2 papers, 2024 to 2025). A disease of the muscle in which the muscle fibers do not function properly. "This distinction sets the CIAO1 myopathy apart from the classical mitochondrial Fe-S–associated myopathies like the ISCU and FDX2 myopathies." (PMID 38950322, 2024).
tumor (2 papers, 2024 to 2026). "On the other hand, the expression levels of CIAO1 and DPYD in CM have demonstrated a positive correlation with tumor prognostic risk." (PMID 38874871, 2024). "CIAO1 also affects tolerance and toxicity of fluoropyrimidines in tumor patients." (PMID 38874871, 2024).
infection (1 paper, 2018). The state of being infected such as from the introduction of a foreign agent such as serum, vaccine, antigenic substance or organism. "Also, in TBEV infection, viperin requires CIAO1 for [4Fe–4S] cluster assembly to selectively blocks positive-sense RNA amplification during the early stages of infection." (PMID 30587778, 2018).
neurodegenerative disease (1 paper, 2024). A disorder of the central nervous system characterized by gradual and progressive loss of neural tissue and neurologic function. "In particular, the recently reported implication of CTC genes ciao-1 and mms-19 in the onset of lethal neurodegenerative diseases highlights the significance of the work presented herein in assisting the study of human disease mechanisms." (PMID 39011897, 2024).
CIAO1 also shares sentences with these, for which no sentence is quoted: anemia (1 paper); Arthritis (1); Friedreich ataxia (1); Iron overload (1); learning disabilities (1); malaria (1); microcephaly (1); prostate carcinoma (1); xeroderma pigmentosum (1).